MYOF (myoferlin)
Diseases named in the same sentence as MYOF in open-access papers (continued):
Sharing a sentence is not in itself a finding about the gene and the disease.
hereditary angioedema (7 papers, 2021 to 2025). Hereditary angioedema (HAE) is a genetic disease characterized by the occurrence of transitory and recurrent subcutaneous and/or submucosal edemas resulting in swelling and/or abdominal pain. "Hereditary angioedema (HAE) with mutations in the myoferlin gene (HAE-MYOF) is one of eight types of HAE." (PMID 39982357, 2025). "According to the most recent classification, hereditary angioedema (HAE) with a mutation in the myoferlin (MYOF) gene (HAE-MYOF) is categorized as angioedema (AE) caused by intrinsic vascular endothelium (VE) dysfunction (AE-VE)." (PMID 40797221, 2025). "The group will then develop pathogenicity classification rules to curate variants in genes responsible for Hereditary Angioedema with normal C1-INH (nl-C1-INH-HAE), such as F12, PLG, ANGPT1, KNG1, MYOF, and HS3ST6 (OMIM: 610618, 619360, 619361, 619363, 619366, 619367)." (PMID 38124188, 2023). "Hereditary angioedema due to C1 Inhibitor deficiency shares a common kinin dependency with other HAE situations: F12-HAE, PLG-HAE, KNG1-HAE, ANGPT1-HAE, and HS3ST6-HAE, but not with MYOF-HAE, U-HAE." (PMID 35958943, 2022).
pancreatic ductal adenocarcinoma (7 papers, 2018 to 2025). An infiltrating adenocarcinoma that arises from the epithelial cells of the pancreas. "For example, WJ460, a strong inhibitor of myoferritin (MYOF), causes mitophagy in pancreatic ductal adenocarcinoma (PDAC) cells, which results in cell death." (PMID 38262996, 2024). "It triggers mitophagy and induces accumulation of ROS by targeting myoferlin in pancreatic ductal adenocarcinoma (PDAC), which eventually causes lipid peroxidation and ferroptosis." (PMID 38262996, 2024). "Both genetic depletion of myoferlin in the murine tumor stroma and the pharmacological targeting of myoferlin alike reduced tumor desmoplasia in orthotopic mouse model of pancreatic ductal adenocarcinoma." (PMID 41062852, 2025).
hepatocellular carcinoma (6 papers, 2018 to 2022). A malignant tumor that arises from hepatocytes. "MYOF is overexpressed in multiple types of cancer including breast, pancreatic, oropharyngeal squamous cell, and hepatocellular carcinomas." (PMID 29721195, 2018). "MYOF is overexpressed in many epithelial cancers, including invasive mammary and pancreatic adenocarcinomas, oropharyngeal squamous cell carcinoma, and hepatocellular carcinoma." (PMID 29721195, 2018). "In the hepatocellular carcinoma (HCC) cell line, the silencing of the transcriptional coactivator of the serum response factor (SRF), Megakaryoblastic Leukemia 1/2 (MKL1/2), induced a reduction of myoferlin gene expression." (PMID 31443490, 2019).
melanoma (6 papers, 2018 to 2022). A malignant, usually aggressive tumor composed of atypical, neoplastic melanocytes. "Therefore, this study aims to investigate the correlation between MYOF and VM in human melanoma tissues and reveal the underlying mechanisms." (PMID 29164766, 2018). "In melanoma cell line (A374), knockdown of MYOF suppressed vasculogenic mimicry via reducing matrix metalloproteinase -2 (MMP-2) and increasing mesenchymal-epithelial transition." (PMID 31477752, 2019). "The pathological investigation showed that the expression of MYOF was dramatically elevated in melanoma tissues." (PMID 29164766, 2018). "VM structures were found in 14 of 52 tested melanoma samples, and high MYOF expression correlated with VM structures." (PMID 29164766, 2018). "Specifically, MYOF‐positive staining was found in 22 samples, among which 17 cases were accompanied with recurrence or metastasis, suggesting that MYOF is overexpressed during melanoma tumorigenesis." (PMID 29164766, 2018). "The melanoma tissues overexpressing MYOF are prone to form VM channels, and this formation is accompanied by an increase in MMP‐2 secretion and loss of E‐cadherin at adherens junctions." (PMID 29164766, 2018). "According to Kaplan–Meier survival curves, VM channels and elevated MYOF expression both correlated with poor prognosis in melanoma patients." (PMID 29164766, 2018). "Therefore, the expression of MYOF in melanoma tissues and the connection between MYOF and VM were examined in this study." (PMID 29164766, 2018). "The expression of MYOF was determined by IHC in 52 melanoma tissue samples." (PMID 29164766, 2018). "All above results suggest MYOF may play a role in VM formation in melanoma." (PMID 29164766, 2018). "However, the expression and role of MYOF in melanoma are largely unknown." (PMID 29164766, 2018). "In conclusion, MYOF plays an important role in VM and knockdown of MYOF suppresses VM formation via decreasing MMP‐2 and inducing MET in A375 melanoma cells." (PMID 29164766, 2018). "Myoferlin (MYOF), a type II membrane protein involved in membrane regeneration and repair, is elevated in several malignant tumours, especially in advanced melanomas." (PMID 29164766, 2018). "Myoferlin (MYOF) is a 230 kDa transmembrane multi-C2-domain protein that contributes to plasma membrane repair, fusion, and endocytosis and is overexpressed in several invasive cancer cell lines, including breast, pancreas, and malignant melanoma." (PMID 31477752, 2019).
colon cancer (5 papers, 2019 to 2025). "Our results highlight for the first time an association between myoferlin expression and survival of colon cancer patients and show a consistent higher expression of this protein in tumour tissue in comparison with the non-tumoural adjacent one." (PMID 30850580, 2019). "In this study, we showed that myoferlin expression in colon cancer lesions is associated with low patient survival and is higher than in non-tumoural adjacent tissue." (PMID 30850580, 2019). "Human colon cancer cells silenced for myoferlin exhibit a reduced oxidative phosphorylation activity associated with mitochondrial fission leading, ROS accumulation, decreased cell growth, and increased apoptosis." (PMID 30850580, 2019). "We have found out that myoferlin expression is highly expressed in colon cancer and correlates with patient survival." (PMID 30850580, 2019). "In colon cancer, MYOF silencing leads to accumulation of reactive oxygen species (ROS) and DNA damage." (PMID 31828126, 2019). "Accordingly, we next evaluated mitochondrial oxygen consumption rate (OCR) and mitochondrial network integrity after myoferlin silencing in colon cancer cell lines expressing highly this protein: HCT116 and SW480." (PMID 30850580, 2019). "We next explored the consequences of the mitochondrial alterations induced by myoferlin silencing in colon cancer cells." (PMID 30850580, 2019). "Myoferlin silencing in colon cancer cells reduces OXPHOS activity and disturbs the mitochondrial dynamics leading to mitochondrial fission." (PMID 30850580, 2019). "The recent identification of a compound interacting with a myoferlin C2 domain and bearing anticancer potency identifies, together with our demonstration, this protein as a suitable new therapeutic target in colon cancer." (PMID 30850580, 2019). "We then sought to evaluate myoferlin abundance in a collection of colon cancer specimens (n = 28)." (PMID 30850580, 2019). "In the continuity of our previous studies aiming at showing the importance of myoferlin in cancer aggressiveness and inspired by the lack of information regarding its expression in colon cancer, we have sought to investigate this protein in this context." (PMID 30850580, 2019).
lung carcinoma (5 papers, 2014 to 2025). "This is the first report to indicate that TRIM8 degrades its substrate, MYOF, through K48-linked ubiquitination to inhibit lung cancer cell mobility." (PMID 39934162, 2025). "This study is the first to identify the novel TRIM8-interacting protein MYOF and to clarify that TRIM8 regulates lung cancer metastasis through the K48-linked ubiquitin-mediated degradation of MYOF." (PMID 39934162, 2025). "Overexpression of MYOF reversed the inhibitory effect of TRIM8 on the motility of lung cancer cells in vitro." (PMID 39934162, 2025). "TRIM8 overexpression in lung cancer cells reduced MYOF expression, and restoring MYOF rescued cell migration in TRIM8-overexpressing cells." (PMID 39934162, 2025). "Moreover, by performing Transwell assays with matrix gels, we confirmed that restoring MYOF expression rescued the invasive capability of lung cancer cells that was suppressed by TRIM8." (PMID 39934162, 2025). "Moreover, for the first time, we demonstrated that TRIM8 plays a pivotal role in suppressing lung cancer metastasis through ubiquitin-mediated degradation of MYOF." (PMID 39934162, 2025). "As anticipated, MYOF knockdown decreased the proliferation and migration of H358 lung cancer cells compared to the control group, regardless of whether a mixture or single siRNAs were used." (PMID 39934162, 2025).
oropharyngeal squamous cell carcinoma (5 papers, 2016 to 2022). "In this study, we examined expression profile of myoferlin in oropharyngeal squamous cell carcinoma (OPSCC) and assessed its correlation with disease progression and patient outcome." (PMID 26919244, 2016). "In this study, we examined the expression of myoferlin in surgically treated oropharyngeal squamous cell carcinoma samples and correlated that with survival, HPV status, and other clinical and pathological variables." (PMID 26919244, 2016). "Kumar et al45 demonstrated that myoferlin could exist in the nucleus, cytosol or membrane of oropharyngeal squamous cell carcinoma (OPSCC) cells." (PMID 31475450, 2019). "In oropharyngeal squamous cell carcinoma (OPSCC), nuclear location of MYOF is significantly related to poor prognosis, as patients with nuclear MYOF+/IL-6+OPSCC have the worst, whereas nuclear MYOF−/IL-6−OPSCC have the best outcome." (PMID 31828126, 2019). "To evaluate the expression pattern and clinical importance of myoferlin, IL-6 and nanog in HNSCC, we assessed the expression of these biomarkers in TMA's constructed using 211 surgically treated oropharyngeal squamous cell carcinoma samples." (PMID 26919244, 2016).
angioedema (4 papers, 2025). Swelling involving the deep dermis, subcutaneous, or submucosal tissues, representing localized edema. "The exon 7 missense c.651G > T;p.Arg217Ser variant of the MYOF gene located on chromosome 10 was identified in three HAE-nC1INH patients from one Italian family, one more member of which was an angioedema-free carrier of the variant." (PMID 40053270, 2025). "This category includes angioedema due to the mutation of angiopoietin-1 (HAE-ANGPT1), myoferlin (HAE-MYOF), and heparan sulfate-glucosamine 3-O sulfotransfersase (HAE-HS3ST6), which are structural endothelial proteins that bind kininogen." (PMID 40426779, 2025). "While it is possible that some patients with these additional mutations may have been misclassified, it is unlikely considering the low frequencies of mutations in MYOF and HS3ST6 genes among patients with nC1INH angioedema." (PMID 40469312, 2025). "MYOF variant p.Arg217Ser has been reported as a cause of HAE-nC1INH in an Italian family (mother and two daughters with history of recurrent angioedema without urticaria)." (PMID 40053270, 2025).
colorectal cancer (3 papers, 2021 to 2025). A primary or metastatic malignant neoplasm that affects the colon or rectum. "Our study highlights the pivotal role of MYOF in regulating PD-L1 expression and reprogramming the colorectal cancer microenvironment." (PMID 39941891, 2025). "In the present study, we further explored that MYOF inhibition suppressed the formation of MYOF‐Rab7 complex and the co‐localization of Rab7 to the late endosome in colorectal cancer cells." (PMID 33634965, 2021). "Impressively, the excellent therapeutic efficacy of YQ456 in a PDX mouse model implies a promising clinical therapeutic prospect of targeting MYOF in colorectal cancer." (PMID 33634965, 2021). "A previous work illustrated that MYOF inhibits cell proliferation in colorectal cancer by modulating OXPHOS." (PMID 33634965, 2021). "In the present study, we provided the first functional evidence that MYOF promoted the cell invasion of colorectal cancer." (PMID 33634965, 2021). "In summary, we have identified a novel potent and selective inhibitor of MYOF to treat colorectal cancer with significant anti‐tumor activities and low toxicity." (PMID 33634965, 2021). "Evidence from the UALCAN and The Human Protein Atlas databases presented that the expression of MYOF in colorectal cancer tissues was higher than that in normal tissues." (PMID 33634965, 2021). "Colorectal cancer cell lines showed higher expression levels of MYOF than NCM460 cell line (Human normal colon epithelial cell line)." (PMID 33634965, 2021). "The present study unveiled that MYOF inhibition prevents the secretion and internalization of exosomes in colorectal cancer cells." (PMID 33634965, 2021). "For example, a genetic mouse model with intrinsic metastasis development will facilitate the functional exploration of MYOF in the spontaneous metastasis of colorectal cancer." (PMID 33634965, 2021). "In summary, YQ456 restrains the invasion and infiltration of colorectal cancer cells by targeting MYOF." (PMID 33634965, 2021). "The expression level of MYOF was positively correlated with the metastatic capacity of colorectal cancer in the UALCAN database and the poor clinical survival of colorectal cancer patients in the OncoLnc database (lower percentile: 7, upper percentile: 10)." (PMID 33634965, 2021). "In our present work, we have investigated the crucial roles of MYOF in colorectal cancer cell invasiveness." (PMID 33634965, 2021). "Therefore, YQ456 affects multiple functions of Rab7 and Rab32 by targeting MYOF, thereby preventing colorectal cancer progression." (PMID 33634965, 2021). "However, our data retrieved from the cBioPortal for Cancer Genomics database presented a significant positive relationship between MYOF and Rab7A in colorectal cancer." (PMID 33634965, 2021). "As the first attempt, the anticancer efficacy of YQ456 in the patient‐derived xenograft (PDX) mouse model indicated that targeting MYOF may serve as a novel and practical therapeutic approach for colorectal cancer." (PMID 33634965, 2021). "Besides, CT26‐Luc cells with sgMYOF treatment showed reduced metastatic potential compared with parent CT26‐Luc cells, implying that MYOF played a pivotal role in colorectal cancer metastasis." (PMID 33634965, 2021). "Therefore, YQ456 targets MYOF to prevent exosome secretion and exosome internalization, thereby suppressing the proliferation and invasion capacities of colorectal cancer cells." (PMID 33634965, 2021). "We proved that targeting MYOF prevents the cell invasion of colorectal cancer." (PMID 33634965, 2021). "However, the precise mechanisms of MYOF in the cell invasiveness of colorectal cancer remain uncertain." (PMID 33634965, 2021). "Additionally, this study provides in vivo evidence that the expression level of MYOF is proportional to the invasive capacity of colorectal cancer cells." (PMID 33634965, 2021).
colorectal cancer (continued). "Therefore, we hypothesized that MYOF may modulate exosome secretion of colorectal cancer cells by disturbing the regulatory function of Rab7." (PMID 33634965, 2021). "Therefore, YQ456 targeting MYOF provides a promising therapeutic approach for colorectal cancer." (PMID 33634965, 2021). "Although the role of MYOF in colorectal cancer metastasis has not been revealed, studies have explored that MYOF promotes cancer metastasis in several cancer types." (PMID 33634965, 2021). "However, the roles of MYOF in colorectal cancer invasion remain enigmatic, and MYOF‐targeted therapy in this malignancy has not been explored." (PMID 33634965, 2021).
head and neck squamous cell carcinoma (3 papers, 2019 to 2023). A squamous cell carcinoma that arises from any of the following anatomic sites: lip and oral cavity, nasal cavity, paranasal sinuses, pharynx, larynx, and salivary glands. "Myoferlin has been found to be highly expressed in several types of cancer, including kidney, liver, pancreatic, breast, and head and neck squamous cell carcinomas." (PMID 37538852, 2023). "Experimentally, a myoferlin gene was discovered as highly expressed in several tumour tissues including the pancreas, breast, kidneys, and head and neck squamous cell carcinoma (HNSCC)." (PMID 31443490, 2019). "Yadav et al46 found that myoferlin is bound to EHD2 protein and modulates the IL‐6/STAT3 signalling pathway, which regulates the expression of IL‐6/STAT3 downstream genes, including snail and nanog, in head and neck squamous cell carcinoma (HNSCC) cell lines." (PMID 31475450, 2019).
liver cancer (3 papers, 2019 to 2025). An epithelial or non-epithelial malignant neoplasm that arises from the liver. "In liver cancer cells, the MRTF–SRF target gene myoferlin promotes cell proliferation by suppressing oncogene-induced senescence, but myoferlin expression was not affected in our MRTF-null MEFs." (PMID 41200793, 2025). "MKL1 can also activate the transcription of deleted in liver cancer (DLC1) and myoferlin to defy oncogenic senescence and preserve cancer cell viability." (PMID 32984327, 2020).
osteoporosis (3 papers, 2022 to 2025). A condition of reduced bone mass, with decreased cortical thickness and a decrease in the number and size of the trabeculae of cancellous bone (but normal chemical composition), resulting in increased fracture incidence. "Our previous study verified that APPL1/myoferlin deficiency promotes adipogenic differentiation of MSCs by blocking autophagic flux in osteoporosis." (PMID 37187293, 2023). "Our previous study verified that Adaptor protein, phosphotyrosine interacting with PH domain and leucine zipper 1 (APPL1)/myoferlin deficiency promotes adipogenic differentiation of MSCs by blocking autophagic flux in osteoporosis." (PMID 37187293, 2023). "Our previous study has shown that the impairment of APPL1/myoferlin facilitates adipogenic differentiation of MSCs by blocking autophagic flux in osteoporosis." (PMID 37187293, 2023). "Thus, the APPL1/MYOF axis may be a promising target for the clinical diagnosis and treatment of osteoporosis." (PMID 35984564, 2022). "Our previous study showed that the expression of APPL1 was downregulated in osteoporosis and that the impairment of APPL1/myoferlin facilitates adipogenic differentiation of MSCs by blocking autophagic flux." (PMID 37187293, 2023).
squamous cell carcinoma (3 papers, 2018 to 2025). A carcinoma arising from squamous epithelial cells. "In immunohistochemical results from patients with non-small cell lung cancer (adenocarcinoma and squamous cell carcinoma), MYOF and VEGFR2 expression were positively correlated." (PMID 39941891, 2025).
breast tumor (2 papers, 2012 to 2014). "We provide in silico and experimental evidence that MYOF plays a critical and previously unrecognized role in breast tumor cell invasion." (PMID 22761893, 2012). "We probed the invasive capacity of breast tumor cells (MDA-MB-231) following shRNA directed depletion of MYOF (shRNAMYOF), and noted a profound deficit in the ability of cells to invade through Matrigel (basement membrane mimic) and collagen type I (stromal ECM mimic)." (PMID 22761893, 2012).